OPRK1 (opioid receptor kappa 1)
Description:
G protein-coupled opioid receptor that functions as a receptor for endogenous alpha-neoendorphins and dynorphins, but has low affinity for beta-endorphins. Also functions as a receptor for various synthetic opioids and for the psychoactive diterpene salvinorin A. Ligand binding causes a conformation change that triggers signaling via guanine nucleotide-binding proteins (G proteins) and modulates the activity of down-stream effectors, such as adenylate cyclase. Signaling leads to the inhibition of adenylate cyclase activity. Inhibits neurotransmitter release by reducing calcium ion currents and increasing potassium ion conductance. Plays a role in the perception of pain. Plays a role in mediating reduced physical activity upon treatment with synthetic opioids. Plays a role in the regulation of salivation in response to synthetic opioids. May play a role in arousal and regulation of autonomic and neuroendocrine functions.
Synonyms: K-OR-1; KOR-1; OPRK; KOR; KOP; KOR1
Tractability: Small molecule: an approved drug acts on it; a structure with a bound ligand is known; a high-quality ligand is known; it belongs to a druggable protein family. Antibody: UniProt places it where antibodies can reach, with high confidence; its Gene Ontology location is reachable by antibodies, with high confidence; UniProt predicts a signal peptide or a membrane-spanning region; the Human Protein Atlas places it where antibodies can reach. PROTAC: ubiquitination databases record sites on it; a small molecule that binds it is known. Other modalities: an approved drug acts on it.
Target class: Short peptide receptor (family A GPCR); Family A G protein-coupled receptor; Peptide receptor (family A GPCR); Opioid receptor; Membrane receptor
Chemical probes: CHEMBL2180640, HS665 (high quality), ICI-199441 (high quality), ML 190 (high quality), ML138, ML139, ML140, ML350, SALVINORIN A (high quality)
Safety:
Unwanted effects reported when the protein is acted on. In parentheses: how it was acted on, where the effect was seen, and who reports it.
dizziness (Bowes et al. (2012): activation, cardiovascular system, central nervous system, gastrointestinal; Lynch et al. (2017): activation, acute dosing, nervous system, cardiovascular, gastrointestinal; Urban et al. (2012): activation, cardiovascular system, nervous system)
dysphoria (Urban et al. (2012): activation, cardiovascular system, nervous system; Bowes et al. (2012): activation, cardiovascular system, central nervous system, gastrointestinal; Lynch et al. (2017): activation, acute dosing, nervous system, cardiovascular, gastrointestinal)
confusion (Lynch et al. (2017): activation, acute dosing, nervous system, cardiovascular, gastrointestinal; Bowes et al. (2012): activation, cardiovascular system, central nervous system, gastrointestinal)
sedation (Bowes et al. (2012): activation, cardiovascular system, central nervous system, gastrointestinal; Urban et al. (2012): activation, cardiovascular system, nervous system)
tachycardia (Urban et al. (2012): activation, cardiovascular system, nervous system; Bowes et al. (2012): activation, cardiovascular system, central nervous system, gastrointestinal)
analgesia (activation; cardiovascular system, nervous system; source: Urban et al. (2012))
antipruritic effects (activation; cardiovascular system, nervous system; source: Urban et al. (2012))
decreased anxiety (inhibition, acute dosing; nervous system, cardiovascular, gastrointestinal; source: Lynch et al. (2017))
decreased blood pressure (activation, acute dosing; nervous system, cardiovascular, gastrointestinal; source: Lynch et al. (2017))
decreased body temperature (activation, acute dosing; nervous system, cardiovascular, gastrointestinal; source: Lynch et al. (2017))
decreased cardiac contractility (activation, acute dosing; nervous system, cardiovascular, gastrointestinal; source: Lynch et al. (2017))
decreased convulsions (activation, acute dosing; nervous system, cardiovascular, gastrointestinal; source: Lynch et al. (2017))
decreased drinking (inhibition, acute dosing; nervous system, cardiovascular, gastrointestinal; source: Lynch et al. (2017))
decreased eating (inhibition, acute dosing; nervous system, cardiovascular, gastrointestinal; source: Lynch et al. (2017))
decreased gastrointestinal motility (activation; cardiovascular system, central nervous system, gastrointestinal; source: Bowes et al. (2012))
decreased gastrointestinal transit (activation, acute dosing; nervous system, cardiovascular, gastrointestinal; source: Lynch et al. (2017))
decreased inflammation (activation, acute dosing; nervous system, cardiovascular, gastrointestinal; source: Lynch et al. (2017))
decreased locomotion (activation; cardiovascular system, central nervous system, gastrointestinal; source: Bowes et al. (2012))
decreased locomotor activity (activation, acute dosing; nervous system, cardiovascular, gastrointestinal; source: Lynch et al. (2017))
decreased pain (activation, acute dosing; nervous system, cardiovascular, gastrointestinal; source: Lynch et al. (2017))
decreased then increased drinking (activation, acute dosing; nervous system, cardiovascular, gastrointestinal; source: Lynch et al. (2017))
decreased/increased heart rate (activation, acute dosing; nervous system, cardiovascular, gastrointestinal; source: Lynch et al. (2017))
diuresis (activation; cardiovascular system, nervous system; source: Urban et al. (2012))
drug abuse/dependence (activation, acute dosing; nervous system, cardiovascular, gastrointestinal; source: Lynch et al. (2017))
hallucinations (activation, acute dosing; nervous system, cardiovascular, gastrointestinal; source: Lynch et al. (2017))
hypotension (activation; cardiovascular system, nervous system; source: Urban et al. (2012))
increased anxiety (activation, acute dosing; nervous system, cardiovascular, gastrointestinal; source: Lynch et al. (2017))
increased convulsions (inhibition, acute dosing; nervous system, cardiovascular, gastrointestinal; source: Lynch et al. (2017))
increased pain (inhibition, acute dosing; nervous system, cardiovascular, gastrointestinal; source: Lynch et al. (2017))
increased urinary output (activation; cardiovascular system, central nervous system, gastrointestinal; source: Bowes et al. (2012))
and 9 more effects
Gene: Protein-coding gene on chromosome 8 (53,225,724 to 53,251,637, reverse strand). Ensembl gene ENSG00000082556.
Subcellular location: Cell membrane
Subcellular location (Human Protein Atlas): Plasma membrane; Cytosol; Nucleoplasm
Pathways (Reactome):
Signal Transduction: G alpha (i) signalling events; Peptide ligand-binding receptors
Gene Ontology:
Molecular function: dynorphin receptor activity; G protein-coupled opioid receptor activity; protein binding; neuropeptide binding; G protein-coupled peptide receptor activity; G protein-coupled receptor activity; receptor serine/threonine kinase binding
Biological process: adenylate cyclase-inhibiting opioid receptor signaling pathway; defense response to virus; G protein-coupled opioid receptor signaling pathway; immune response; adenylate cyclase-inhibiting G protein-coupled receptor signaling pathway; chemical synaptic transmission; locomotory behavior; neuropeptide signaling pathway; phospholipase C-activating G protein-coupled receptor signaling pathway; regulation of saliva secretion; sensory perception; sensory perception of pain; behavioral response to cocaine; cellular response to glucose stimulus; cellular response to lipopolysaccharide; conditioned place preference; eating behavior; estrous cycle; G protein-coupled receptor signaling pathway; maternal behavior; negative regulation of luteinizing hormone secretion; positive regulation of dopamine secretion; positive regulation of eating behavior; positive regulation of p38MAPK cascade; positive regulation of potassium ion transmembrane transport; and 7 more
Cellular component: membrane; plasma membrane; neuron projection; axon terminus; dendrite; mitochondrion; neuronal cell body; perikaryon; postsynaptic membrane; presynaptic membrane; sarcolemma; sarcoplasmic reticulum; synaptic vesicle membrane; T-tubule
Genetic constraint (gnomAD): Loss-of-function variants: 16 observed, 26.8 expected, observed/expected ratio (o/e) 0.6, 90% interval 0.4 to 0.91. The upper end of that interval is the gene's LOEUF score, 0.91, which puts it in group 3 of 6, group 1 being the genes least tolerant of losing a copy. Missense variants: 479 observed, 527.88 expected, observed/expected ratio (o/e) 0.91, 90% interval 0.84 to 0.98. Synonymous variants: 205 observed, 207.1 expected, observed/expected ratio (o/e) 0.99, 90% interval 0.88 to 1.11.
Homologues: Orthologues: chimpanzee OPRK1 (99% identical), macaque OPRK1 (98% identical), rabbit OPRK1 (95% identical), rat Oprk1 (94% identical), mouse Oprk1 (94% identical), pig OPRK1 (94% identical), guinea pig OPRK1 (93% identical), dog OPRK1 (93% identical), tropical clawed frog oprk1 (77% identical), zebrafish oprk1 (68% identical), Caenorhabditis elegans trhr-1 (23% identical), Drosophila melanogaster Rh7 (20% identical). Paralogues in human: OPRM1 (58% identical), OPRD1 (56% identical), OPRL1 (50% identical), SSTR1 (35% identical), SSTR4 (34% identical), SSTR2 (34% identical), SSTR3 (32% identical), NPBWR2 (31% identical), SSTR5 (31% identical), NPBWR1 (29% identical), KISS1R (27% identical), CMKLR2 (25% identical), and 5 more.
Diseases named in the same sentence as OPRK1 in open-access papers:
OPRK1 is named in the same sentence as 137 diseases in open-access papers, as found by Europe PMC text mining. Sharing a sentence is not in itself a finding about the gene and the disease. The quoted sentences say what the papers report.
Anxiety (62 papers, 2009 to 2026). Intense feelings of nervousness, tension, or panic often arise in response to interpersonal stresses. "We demonstrate that reduced KOR expression through genetic inactivation of the KOR encoding gene, Oprk1, in the CeA results in increased anxiety-like behavior and impaired conditioned threat discrimination." (PMID 33323398, 2021). "To examine the role of CeA KOR and dynorphin in discriminative fear learning and anxiety-like behavior, we reduced Oprk1 and Pdyn expression in the CeA by injecting floxed Oprk1 and floxed Pdyn mice with and adeno-associated virus (AAV) containing an expression cassette for Cre-EGFP (AAV1-Cre-EGFP)." (PMID 33323398, 2021). "22,23 However, a study from the Zweifel lab found that genetic deletion of Oprk1 increases anxiety-like behavior in mice, suggesting a potential complex anxiety/alcohol intake interaction." (PMID 38352404, 2024). "Some studies report that site specific manipulations of Oprk1 can mediate anxiety-like behavior, the effects of social defeat stress, and the extent to which social play is rewarding." (PMID 23717492, 2013). "Baseline anxiety-like behaviors and nociceptive thresholds are unaltered in Oprk1-Cre mice." (PMID 37364995, 2023). "To determine whether KOR signaling in the CeA regulates anxiety-like behavior and conditioned threat discrimination, we inactivated Oprk1 by injecting Oprk1lox/lox mice with AAV1-Cre-EGFP bilaterally into the CeA." (PMID 33323398, 2021). "Because of the high levels of Oprk1 expression in the adjacent BLA and the known role of BLA KOR in regulating fear and anxiety, we used a dilute virus and excluded all mice with viral spread into adjacent structures." (PMID 33323398, 2021). "We also show that Cre insertion into the Oprk1 locus does not alter KOR function or baseline anxiety-like and pain-like behaviors." (PMID 37364995, 2023). "Activation led to decreased anxiety-like behavior on the elevated plus maze and increased sociability in female but not in male Oprk1-Cre mice." (PMID 37364995, 2023).
depression (55 papers, 2012 to 2026). "DUSP6 overexpression also increased mRNA levels for the kappa opioid G-protein coupled receptor, which has been implicated in memory and depression, and additionally, OPRK1 promoter methylation that leads to reduced gene expression has been found to increase AD risk." (PMID 39006222, 2024).
alcohol dependence (18 papers, 2012 to 2025). Physical and psychological dependence on alcohol. "Effects of PDYN and OPRK1 single-nucleotide polymorphisms (SNPs) strongly associated with alcoholism on expression of both genes were also studied." (PMID 29925858, 2018). "Previous studies found associations between the broad phenotype of alcohol dependence and sequence variation in human OPRK1 (encoding KOR) and PDYN genes." (PMID 24223163, 2013). "Genetic studies associate polymorphisms in the PDYN gene and OPRK1, the KOR-encoding gene with heroin addiction, alcoholism, novelty seeking and positive reward traits." (PMID 34200173, 2021). "The effect of alcoholism on the slope of the correlation between PDYN and OPRK1, manifested as significant alcoholism × OPRK1 interaction, suggests that alcoholics with high OPRK1 expression have greater PDYN mRNA levels than respective controls." (PMID 29383684, 2018). "We first examined whether expression of PDYN and OPRK1—calculated for the whole tissue and also adjusted for changes in cell composition—was affected by alcoholism." (PMID 29383684, 2018). "Thus, we examined whether transcription of the opioid PDYN and OPRK1 genes and dopamine receptor genes is coordinated in this neural microcircuitry, and if so, whether their co-expression patterns are affected by alcoholism." (PMID 29383684, 2018). "Effects of alcoholism on the whole tissue levels of PDYN and OPRK1 mRNAs in dlPFC were examined after adjusting for demographical data and tissue characteristics including age, PMI, brain pH, and RQI." (PMID 29925858, 2018). "Effects of alcoholism on the whole tissue levels of PDYN, OPRK1, DRD1, and DRD2 mRNAs in NAc were examined after adjusting for demographical data and tissue characteristics including age, PMI, brain pH, and RQI." (PMID 29383684, 2018). "PDYN mRNA significantly correlated with OPRK1 mRNA (P = 2 × 10−6), and there was a significant effect of interaction between alcoholism and PDYN–OPRK1 correlation (P = 0.011)." (PMID 29383684, 2018).
dependence (5 papers, 2012 to 2023). "The weaker role of OPRK1 variants in substance dependence observed in this study agrees with the findings in previous neuropsychopharmacological studies that the κ-opioid receptor seemed to mediate psychotomimetic effects, which do not have a clear relation to risk of substance dependence." (PMID 24533225, 2013).
Obesity (5 papers, 2019 to 2025). Accumulation of substantial excess body fat. "Other GPCRs involved in neurohormonal signalling and associated with obesity and insulin resistance, such as OPRK1 and ADRB2, and receptors for peptide hormones, including somatostatin (SSTR1/2/5) and secretin (SCTR), were also enriched in K cells." (PMID 39441374, 2025).
breast carcinoma (4 papers, 2021 to 2025). "Furthermore, OPRK1 has been implicated in facilitating the migration of breast cancer cells, while the low expression of GABRB1 correlated with a poor prognosis in colon adenocarcinoma." (PMID 37873862, 2023). "Previous studies showed that the migration ability was stronger in MDA-MB-231 cells than MCF-7 cells, and our results suggested the overexpression of OPRK1 might be associated with the migration ability of breast cancer cells." (PMID 34461834, 2021). "However, the effects and underlying mechanisms of opioid receptor κ (OPRK1) in breast cancer remain unknown." (PMID 34461834, 2021). "After qualification of proteins expression, the OPRK1 expressions were higher in breast cancer cells than normal cells." (PMID 34461834, 2021). "In order to determine the effects of OPRK1 on migration of breast cancer cells, the OPRK1 siRNA was used to knockdown the protein expression and compared the changes before transfection." (PMID 34461834, 2021). "In conclusion, our findings illustrated the role of OPRK1 played on promoting migration, and it was overexpression in breast cancer cells in vitro." (PMID 34461834, 2021). "The results suggested that OPRK1 was highly expressed in breast cancer cells both in translation and transcription, compared with the normal cells." (PMID 34461834, 2021). "Our research demonstrated that OPRK1 was overexpressed in breast cancer cells compared with the normal human mammary epithelial cells." (PMID 34461834, 2021). "We compared the differences in expression of OPRK1 in normal cells and breast cancer cells, and determined the cell viability, migration after OPRK1 knockdown using small interfering RNA (siRNAs)." (PMID 34461834, 2021). "Here, we verified the OPRK1 expression was enhanced significantly in breast cancer cells compared with normal cells." (PMID 34461834, 2021). "Here, we investigated the role of PI3K/AKT activation played in breast cancer cell after transfected with OPRK1 siRNA." (PMID 34461834, 2021). "It is indicated that OPRK1 promoted cell migration in breast cancer, suggesting a therapeutic target for breast cancer patients." (PMID 34461834, 2021). "It is suggested that the AKT and PI3K activation could be affected by OPRK1 expression in breast cancer cells, and the activation changed more notable in the cells with high migration ability." (PMID 34461834, 2021). "Here, in this study, we aimed to research the effects of OPRK1 in migration in breast cancer." (PMID 34461834, 2021). "It is suggested that OPRK1 expression promoted cell viability in breast cancer cells." (PMID 34461834, 2021). "And then, we determined whether OPRK1 knockdown affect the migration in breast cancer cells." (PMID 34461834, 2021). "Therefore, knockdown of OPRK1 inhibited the invasion and migration of breast cancer cells in vitro." (PMID 34461834, 2021). "In this study, we aimed to investigated the anti-migration of OPRK1 knockdown in normal cells MCF-10A and breast cancer cell lines." (PMID 34461834, 2021). "Here, the breast cancer cell lines of MDA-MB-231 and MCF-7 were chosen to detected the function of OPRK1 in migration of breast cancer, as MDA-MB-231 cells with high expression of OPRK1 while the expression of OPRK1 in MCF-7 was low." (PMID 34461834, 2021). "The cell lines of breast cancer cells including MDA-MB-231, MDA-MB-435 and MCF-7 cells as well as normal human mammary epithelial cells of MCF-10A was used to determine the protein expression of OPRK1 by western blot and RT-qPCR." (PMID 34461834, 2021). "Furthermore, Due to the essential effects of PI3K/AKT pathway in tumor migration, we also investigated the correlation between OPRK1 and PI3K/AKT pathway, and detected how OPRK1 affected migration of breast cancer cells when AKT activation/inhibition." (PMID 34461834, 2021).
cognitive deficits (4 papers, 2015 to 2023). "In the present study, the Shunaoxin pill active ingredient stigmasterol was found to bind the most stably with the core protein OPRK1 in T2DM-induced cognitive impairment." (PMID 36341127, 2022). "Active ingredients of the Shunaoxin pill may alleviate cognitive impairment in diabetic patients by targeting the proteins OPRK1, GABRA5, GABRP, and SCN3B." (PMID 36341127, 2022). "Thus, the OPRK1 gene may be involved in the development of cognitive impairment in diabetes by affecting β-amyloid." (PMID 36341127, 2022).
drug dependence (4 papers, 2013 to 2018). "In the present study, we further analyzed the interactive effect of OPRM1, OPRD1, and OPRK1 variants on alcohol or drug dependence using a pattern discovery-based method." (PMID 24533225, 2013). "Considering the close biological interaction of the three receptors, we hypothesized that variation in their genes (OPRM1, OPRD1, and OPRK1) might have joint effects on risk for alcohol or drug dependence." (PMID 24533225, 2013).